NOS2 (nitric oxide synthase 2)
Diseases named in the same sentence as NOS2 in open-access papers (continued):
Sharing a sentence is not in itself a finding about the gene and the disease.
cancer (continued). "Furthermore, our study also discovered that under the induction of SPP1, pro-cancer genes such as Arg1 and Nos2 were upregulated in MDSCs, while anti-cancer genes like IL1b and TNFα were downregulated." (PMID 39066845, 2024). "NOS2 expression and NO production drive aggressive cancer phenotypes." (PMID 38645113, 2024). "Additionally, NOS2 can crosstalk with the proinflammatory enzyme cyclooxygenase-2 (COX-2) to promote cancer progression." (PMID 38892290, 2024). "Moreover, previous studies also show significant NOS2 overexpression in cells of various cancers, including BC cells." (PMID 37660159, 2023). "Likewise, our study revealed NOS2 as a promising candidate for expanding the arsenal of treatment options against HB and other cancers." (PMID 37795447, 2023). "Nevertheless, NOS2 exhibited a relatively low methylation level in most cancers." (PMID 36518255, 2022). "NOS2 is an inducible nitric oxide synthase, and as a pro-inflammatory mediator, NOS2 may promote cancer initiation and progression." (PMID 35265525, 2022). "An example is in cancer models and tuning the immune system where the role of arginine is to promote either immune suppression through polyamine synthesis or immune activation in myeloid cells through NOS2." (PMID 34209132, 2021). "The dual role of NOS2 in cancer development is known in the literature." (PMID 33374571, 2020). "Interestingly, we did not see an increase in expression among genes that are associated with immunosuppression in cancer (such as ARG1, CD274, COX2, PGE2, and NOS2)." (PMID 33659259, 2020). "Potential effect of IL-4 and IL-13 (250 ng/mL, 24 h) on the expression of genes encoding proteins relevant for cancer development by facilitating angiogenesis (HIF1A and VEGFA), inflammation (PTGS2, NOS2, CCL2), and metabolic reprogramming (GLUT1, ODC1, NOS2) was evaluated." (PMID 32512917, 2020). "NOS2 expression in cancer cells often predicts poor patient outcome." (PMID 32423132, 2020). "In addition, elevated coexpression of PTGS2 and NOS2 (51% and 48% of the total compounds, respectively) proteins is a strong predictor of poor survival among cancer patients." (PMID 31949474, 2019). "NOS2 can regulate cancer proliferation via increasing the stability of HIF-1a." (PMID 30381359, 2018). "For example, miR-146b-3p might function to regulate the proliferation of cancers by targeting NOS2 gene in the HIF-1 signalling pathway." (PMID 30381359, 2018). "Indeed, the cytotoxic action of the cytokine interferon gamma (IFN-γ), or the activity of LPS-activated primary mouse macrophages against different cancer cell lines, were impaired in macrophages from NOS2 knock-out mice." (PMID 30082427, 2018). "Moreover, GO analysis suggested that up-regulated CCL2 participated in the chemokine signaling pathway, and down-regulated NOS2 involved cancer and calcium signaling pathways." (PMID 28095896, 2017). "The physiological role of basal induction of the NOS2 gene in human cells is not well studied but has been implicated in changes that lead to cancer." (PMID 25403885, 2014). "Together, these observations indicate that NOS2 expression may have deleterious effects in the progression of certain human cancers including ER- breast cancer." (PMID 22971289, 2012). "Here, we report the findings of the SR/CR mice bred into the knockout backgrounds of Prf-/-, Cybb-/-, and Nos2-/- as it relates to the survival against a primary challenge with S180, and the evaluation of the cancer killing activity of individual leukocyte populations from these mice." (PMID 20356394, 2010). "Therefore, consequences of NOS2-derived NO, which are observed in cancer tissue, may have similar implications in the microenvironment of psoriatic skin." (PMID 38926337, 2024). "Notably, recent studies have demonstrated the possibility of targeting NOS2 in cancer therapy." (PMID 37795447, 2023).
cancer (continued). "In addition, CAFs and cancer cells may secrete exosomes promoting the polarization of macrophages to an M1 (anti-tumoral profile), expressing more NOS2 or M2 (pro-tumoral profile) phenotype, expressing more arginase." (PMID 36831498, 2023). "In addition, NOS2 may be one of the biomarkers and predictors of poor prognosis and an ideal target for cancer therapy." (PMID 35453316, 2022). "Indeed, we observed both in vivo and in vitro that depletion of PMN-MDSCs using cabozantinib resulted in the sensitization of cancer cells to anti-PD-1/PD-L1 treatment that correlated with significant decreases in NOS2 and Arg1 and increased CTL proliferation and effector function." (PMID 33348809, 2020). "Therefore, NOS2 may participate in bone overgrowth after femora fracture via suppressing osteoblast apoptosis through the cancer pathway and calcium pathway." (PMID 28095896, 2017). "NOS2 (inducible NOS) and COX2 promote cancer disease progression and poor survival and play roles during immune suppression in several cancers." (PMID 40663402, 2025). "MDSCs can inhibit Teffs by releasing arginase 1 (Arg1), nitric oxide synthase 2 (NOS2), reactive oxygen species (ROS), cyclooxygenase 2 (COX2), TGF-β, etc., thereby promoting the progression of various cancers." (PMID 40008144, 2025). "This mutual relationship between NOS2 and COX-2 has been identified as a mediator of cancer progression in different cancer types such as head and neck squamous cell carcinoma, breast, colon, and non-small cell lung cancers." (PMID 38892290, 2024). "PDLIM2 has been demonstrated to regulate different signaling pathways, including NF-κB, STAT3, NOS2, TGF-β/Smad, and β-catenin in cancer cells." (PMID 38880883, 2024). "Previous work has shown that NOS2-derived NO and COX2-derived PGE2 collaborate in a feedforward manner to activate multiple oncogenic pathways that promote metastasis, cancer stemness, and immunosuppression, which are all markers of disease progression." (PMID 39356141, 2024). "These nutraceuticals present an opportunity to explore insights gained from spatial analysis of NOS2/COX2 and the chemical biology of NO and PGs for potential therapeutic applications in cancer." (PMID 38892290, 2024). "Understanding the localization of NOS2/COX2 in tumors offers valuable insights and an opportunity to devise new approaches for targeting and preventing the progression of advanced cancers." (PMID 38892290, 2024). "Nitric oxide is a signaling molecule synthesized by three subtypes of NO synthase (NOS1, NOS2, and NOS3) and is increased in various cancers and involved in various cancer processes, such as proliferation and migration." (PMID 38877096, 2024). "Mechanistic analysis suggested that Nos2 and nitric oxide (NO) produced by MDSCs fostered CSC phenotypes via activating Notch and STAT3 pathways in cancer cells." (PMID 37377935, 2023). "Western blotting results showed that NOS2 and ALOXE3 were significantly highly expressed in cancer, and the difference was statistically significant (P < 0.05)." (PMID 35265525, 2022). "In addition to oncogenic signaling mechanisms, NOS2-derived NO can also affect and tune anabolic and catabolic metabolism, including sugar, fatty acid, and amino acid metabolism, which are now considered as novel areas of cancer treatment research for the most clinically challenging cancers." (PMID 34209132, 2021). "First, we grouped the 9736 TCGA cancer cohorts into high or low RNA expressions of EGFR, mTOR, NOS2, TGFB1, mTOR, and FGFR1 and compared the survival of cohorts from the two groups." (PMID 33842373, 2021). "The abnormal expressions of NOS2, DUOX2/DUOXA2, ESR1, EGFR, MYC, and AKT1, which are being discussed in this study, have been confirmed to be related to cancer." (PMID 33299870, 2020). "In our study, NOS2 was 100 to 1000 times more highly expressed than other NOS isoforms in the hematopoietic and cancer cell compartments." (PMID 31481761, 2019).
cancer (continued). "Nitric oxide, a signaling molecule synthesized by three isoforms of NO synthase (NOS1, NOS2 and NOS3), increases in multiple cancers and participates in various cancer processes such as formation, progression and metastasis." (PMID 31805977, 2019). "Moreover, NOS2 seems to be involved in maintaining physiologically relevant levels of NO to sustain the progression phase of carcinogenesis; mainly it is required to promote angiogenesis and to enhance the ability of cancer cells to counteract nutrient paucity in solid tumors and to metastasize." (PMID 30234010, 2018). "Correspondingly, HeLa cells were treated with FSK and probed for its effect on potent established cancer markers like PP2B, IL-6, NOS2, Caspase3, Bcl2, and Bax." (PMID 30558287, 2018). "NOS2-siRNA decreased both OVCAR-3 and Caov-3 cancer cell growth in vivo, in statistically significant fashion." (PMID 26593252, 2016). "Both NOS2 and CD163 have been utilized by others as markers to define M1 or M2 macrophage phenotypes in human cancers." (PMID 23077543, 2012). "Interestingly, TAMs (CCL2, CD86, and IL10), M1 [INOS(NOS2), IRF5, and COX2(PTGS2)] were significantly correlated with SHC1 expression in the three cancers." (PMID 35601500, 2022). "NOS2 is a synthase for protein catalytic reaction, and PTGS2 is a marker of cancer." (PMID 35696640, 2022). "Therefore, in this setting, high levels of miR-155 correlate with high NOS2 in TAMs, and reduced FGF2 expression in EACS overall diminish cancer cell proliferation." (PMID 34200849, 2021). "In cancer cells, inducible NOS (NOS2) expression favors a mesenchymal or CSC-like phenotype." (PMID 34209132, 2021). "In addition, the local expression of key pathway enzymes (ARG1, ARG2, DDAH1, DDAH2, NOS2, ODC1, PRMT1, and PRMT5), as potential therapeutic targets, was evaluated in reference to cancer pathology." (PMID 32872669, 2020). "The localization and distribution of SOD1, NOS2, and COX2, revealed a widespread broadening in bronchiolar and alveolar cells, as well as in the metastatic masses, evidencing the pulmonary reaction to the cancer injury." (PMID 32423132, 2020). "The prognostic value of MMP-9 in different types of cancer has been clearly identified, also demonstrating that its expression promotion and its transformation to active MMP-9, is dependent on NO synthesis, performed by the NOS-2 enzyme." (PMID 31683688, 2019). "Several genes were found to be up-regulated including Nos2, PLAT, and CD34 many of which are involved in Wnt/β catenin signaling, a pathway known to drive cell proliferation and regulate cell-cell adhesion in cancer 29–32." (PMID 31796785, 2019). "Among these anti-cancer targets, 3-phosphoinositide-dependent protein kinase-1(PDPK1), MMP1, MMP2, MMP3, nitric oxide synthase (NOS2), and inosine-5′-monophosphate dehydrogenase 2 (IMPDH2) showed similar binding affinity with bruceantin as that of some marketing drugs." (PMID 24429698, 2014). "This is the first time in which a NOS2 remarkable expression is reported for the histologically normal mucosa surrounding carcinomas." (PMID 24316703, 2014). "When these genetically engineered mice were challenged with cancer cells, the knockout backgrounds of Prf-/-, Cybb-/-, or Nos2-/- did not completely abolish the SR/CR cancer resistant phenotype." (PMID 20356394, 2010). "Although the Ca2+-independent NOS activity, which indicates NOS2 expression, was low or undetectable in non-tumour tissues and most carcinomas, significant activity occurred in three SCC." (PMID 9683299, 1998). "Nitric oxide synthase 2 (NOS2) and cyclooxygenase 2 (COX2) lie at a critical intersection between inflammation, metabolism, and oncogenic signaling, where they cooperatively promote and establish a Nitric Oxide (NO)-driven Warburg phenotype in advanced cancers." (PMID 42248132, 2026).
cancer (continued). "However, cancer tissues expressed mTOR at significantly (p < 0.001) lower levels than adjacent normal tissues in KICH, KIRC, and KIRP; FGFR1 at lower levels in READ and THCA; and NOS2 at lower levels in KICH than adjacent normal tissues." (PMID 33842373, 2021). "Since Nos2 inhibitors were previously shown not to have an effect on macrophage killing in vitro, it is likely that the absence of nitric oxide will only affect neutrophil killing activity during the primary SR/CR response to cancer in vivo." (PMID 20356394, 2010). "For example, miR-146b-3p and miR-4433a-3p could, respectively, target NOS2 (nitric oxide synthase 2) and RPS6KB2 (ribosomal protein S6 kinase B2) of the HIF-1 signalling pathway and the mTOR signalling pathway, leading to the proliferation and invasion of cancers." (PMID 30381359, 2018). "Unlike M1 macrophages, which use Nitric Oxide Synthase 2 (NOS2) to create NO and destroy cancer cells, M2-TAMs metabolize arginine to polyamines through increasing Arginase 1 expression." (PMID 36483029, 2022). "Moreover, miR-30e alters cell proliferation, colony formation and invasiveness in cancer cells, interfering with NF-κB/IκBα negative feedback and apoptosis, suggesting a putative role of NF-κB activation during miR-30e-5p inhibition and increased levels of Nos2." (PMID 30949455, 2019).
bacterial infection (17 papers, 2006 to 2025). "This study aimed to determine the nature of the distribution of relative frequencies of alleles and genotypes of polymorphic PRL and NOS2 in Holstein cows and to identify the relationship of polymorphisms with resistance to viral and bacterial infections." (PMID 36855359, 2023). "In some bacterial infections, an exacerbated expression of NOS2 was associated with a more severe disease outcome, likely due to NO-mediated cytotoxicity and tissue damage and suppression of the immune response to the pathogen." (PMID 27849167, 2016). "NO generated in macrophages by the inducible nitric oxide synthase (iNOS: murine or by the human variant NOS2) and its derivatives are produced in response to bacterial infection." (PMID 21760796, 2011). "NOS2, as an important regulatory factor, has been found to be the target of miR-493-5p and is involved in the inflammatory response during bacterial infection (." (PMID 41430255, 2025). "Though blood neutrophils are not readily equipped with NOS2, it has been shown that they are able to produce NO via NOS2 under different pathological conditions, including bacterial infections." (PMID 35269694, 2022). "In mammals, NO is produced by nitric oxide synthase-2 (NOS2) in macrophages to control bacterial infection, which induces NOS2 transcription." (PMID 35663981, 2022). "Nos2 expression helps to control bacterial infections such as S. aureus and MMP12 plays a role in early killing of S. aureus in the phagolysosome of MΦ." (PMID 27010826, 2016). "The nitric oxide synthase 2A (NOS2A) gene is responsible for the production of nitric oxide under pathological conditions including host defence against bacterial infection." (PMID 19309520, 2009). "Importantly, NOS2-catalyzed reactive nitrogen intermediates have been reported to play important roles in mediating bactericidal activity, inhibiting bacterial infections and regulating inflammatory processes." (PMID 31766159, 2019). "Although it is generally recognized that NOS2 plays an essential role in the host defense against some strains of M. tuberculosis, other studies assign a detrimental role to NOS2 in the context of M. avium infection and other bacterial infections." (PMID 27849167, 2016). "DNA amplification of Holstein cattle for the polymorphic regions of PRL and NOS2 using the PCR-RFLP method revealed a possible connection between the distribution of relative allele frequencies of bPRL and bNOS2 and resistance to viral and bacterial infections." (PMID 36855359, 2023). "The relative MoDC vs. Mo/MP signature encompasses additional genes that participate in “migration of cells” (p = 10−2.3, with S1PR3, CCL17, and SLC2A1), “bacterial infection” (p = 10−3.2, with CD1B, CD209, and FCGR2B), and “synthesis of nitric oxide” (10−2.5, with PLAU, IL1R2, and NOS2)." (PMID 26150816, 2015). "Hence, IFNγ alone is most likely not able to control bacterial infection in vivo in the absence of NOS2." (PMID 32408806, 2020).
inflammation (9 papers, 2008 to 2024). Aberrant reaction of the microcirculation characterized by movement of fluid and leukocytes from the blood into extravascular tissues. "Increased levels of NOS2 have been associated with brain inflammation and neurodegenerative diseases as the mechanism that activated microglia intoxicate neurons in culture has been suggested to involve the increased release of NO." (PMID 34681607, 2021). "This study revealed that uPM10 inhalation to mice enhanced lung tissue levels of the inflammatory COX-2 and NOS2, suggesting that uPM10 caused pulmonary inflammation." (PMID 33809902, 2021). "O3, NO2 and PM2.5 have been shown to induce airway inflammation and oxidative stress in the airways, which then leads to increased production of NO by NOS2." (PMID 38049853, 2023). "Oral administration of indole in mice decreased LPS-induced liver inflammation by reducing hepatic pro-inflammatory gene expression (IL-1b, IL-6, and IL-15) and ameliorated oxidative stress by downregulating the expression genes Nos2 (nitric oxide synthase 2) and Nox2 (NADPH oxidase 2)." (PMID 38283696, 2024). "Peripheral inflammation or sciatic nerve injury did not modify the spinal cord protein levels of NOS2 at 14 or 28 days after CFA-injection or CCI-induction, respectively, which is consistent with a previous study." (PMID 30971925, 2019). "Allergic airway inflammation, as reflected by BAL total cell count, and macrophage and eosinophil numbers, was produced to varying degrees in all mice with systemic sensitization and airway challenge using OVA; however, the total cell count and eosinophil responses were minimal in NOS-2-/- mice." (PMID 18505586, 2008). "Following development of airway inflammation, several strains of mice (MKK3-/-, NOS-2-/-, and NOS-3-/-) had no measurable changes in ECO, in contrast to many others." (PMID 18505586, 2008).
neurological diseases (7 papers, 2009 to 2024). "NOS2 is induced in primary astrocytes under inflammatory conditions and is also implicated in neurological disorders such as multiple sclerosis (MS), cerebral ischemia, and AD." (PMID 39105197, 2024). "AOC1 (ENSG00000002726.20, predicted by LASSO) and another epidemiological factor, NOS2, are the two major factors reported to be associated with the neurological disorders causing taste and smell loss, validating the efficacy and accuracy of our prediction." (PMID 36983953, 2023). "NOS2 isoforms associated with inflammation in brain glial cells are believed to contribute to neurological disorder etiology and progression." (PMID 36081896, 2022). "Nitric oxide synthase type 2 (NOS2) is known for its involvement in various neurological disorders through the generation of nitric oxide (NO)." (PMID 39105197, 2024). "In view of the known involvement of NOS2 in a variety of neurological diseases and conditions, the knowledge that increasing SUMOylation processes can reduce NOS2 expression provides novel targets for therapeutic interventions." (PMID 19323834, 2009). "Cc can treat Mn-induced nervous system diseases through targets such as CASP9, PTGS2, NOS1, and NOS2." (PMID 37904435, 2023). "Our network analysis demonstrated that the most highly correlated targets between Mn-induced nervous system disease-related genes and Cc compound-related genes were CASP9, PTGS2, NOS1 and NOS2, which are primarily involved in oxidative stress and inflammation." (PMID 37904435, 2023).